A2ML1 (alpha-2-macroglobulin like 1)
Description:
Is able to inhibit all four classes of proteinases by a unique 'trapping' mechanism. This protein has a peptide stretch, called the 'bait region' which contains specific cleavage sites for different proteinases. When a proteinase cleaves the bait region, a conformational change is induced in the protein which traps the proteinase. The entrapped enzyme remains active against low molecular weight substrates (activity against high molecular weight substrates is greatly reduced). Following cleavage in the bait region a thioester bond is hydrolyzed and mediates the covalent binding of the protein to the proteinase (By similarity). Displays inhibitory activity against chymotrypsin, papain, thermolysin, subtilisin A and, to a lesser extent, elastase but not trypsin. May play an important role during desquamation by inhibiting extracellular proteases.
Synonyms: CPAMD9; FLJ25179; p170; OMS
Tractability: Antibody: UniProt places it where antibodies can reach, with high confidence; UniProt predicts a signal peptide or a membrane-spanning region; its Gene Ontology location is reachable by antibodies, with medium confidence.
Gene: Protein-coding gene on chromosome 12 (8,822,621 to 8,887,001, forward strand). Ensembl gene ENSG00000166535.
Subcellular location: Secreted
Gene Ontology:
Molecular function: peptidase inhibitor activity; endopeptidase inhibitor activity
Biological process: regulation of endopeptidase activity
Cellular component: extracellular exosome; extracellular region
Genetic constraint (gnomAD): Loss-of-function variants: 145 observed, 174.61 expected, observed/expected ratio (o/e) 0.83, 90% interval 0.73 to 0.95. The upper end of that interval is the gene's LOEUF score, 0.95, which puts it in group 4 of 6, group 1 being the genes least tolerant of losing a copy. Missense variants: 1,594 observed, 1,785.8 expected, observed/expected ratio (o/e) 0.89, 90% interval 0.86 to 0.93. Synonymous variants: 636 observed, 681.56 expected, observed/expected ratio (o/e) 0.93, 90% interval 0.87 to 1.
Gene-disease validity (ClinGen):
ClinGen rates the evidence that A2ML1 causes each of these diseases.
Noonan syndrome (autosomal dominant): Disputed. Noonan Syndrome (NS) is characterized by short stature, typical facial dysmorphism and congenital heart defects.
Homologues: Orthologues: chimpanzee A2ML1 (99% identical), macaque A2ML1 (96% identical), rabbit A2ML1 (84% identical), dog A2ML1 (81% identical), pig A2ML1 (81% identical), zebrafish a2ml (37% identical), zebrafish si:dkey-105h12.2 (37% identical), zebrafish si:dkey-52d15.3 (37% identical), zebrafish si:dkey-46g23.3 (36% identical), zebrafish si:dkey-46g23.2 (35% identical), zebrafish zgc:171445 (35% identical), zebrafish zgc:165518 (35% identical), and 11 more. Paralogues in human: A2M (40% identical), PZP (38% identical), CPAMD8 (27% identical), CD109 (26% identical), C3 (22% identical), C4A (21% identical), C4B (21% identical), C5 (20% identical).
Diseases named in the same sentence as A2ML1 in open-access papers:
A2ML1 is named in the same sentence as 34 diseases in open-access papers, as found by Europe PMC text mining. Sharing a sentence is not in itself a finding about the gene and the disease. The quoted sentences say what the papers report.
otitis media (4 papers, 2016 to 2021). Inflammation of the anatomical structures of the middle ear, which is most often caused by an infectious process. "Recently we identified rare variants in the A2ML1 gene, which encodes alpha-2-macroglobulin-like 1 protein, as a cause of otitis media susceptibility." (PMID 27799062, 2016). "Previously rare A2ML1 variants were identified to confer otitis media susceptibility in an indigenous Filipino community and in otitis-prone US children." (PMID 27799062, 2016). "Moreover, authors investigated microbiota composition in subjects who were carrier of the A2ML1 gene, which encodes an alpha-2 macroglobulin-like 1 protein, previously identified as a genetically determined risk factor for of otitis media." (PMID 32887458, 2020).
Noonan syndrome (3 papers, 2018 to 2024). "Finally, the rs73038782 variant in the A2ML1 host gene, an inhibitor of various proteases and linked with some cases of Noonan syndrome, is enriched in black non-Hispanics from multiplex families without ID." (PMID 38760502, 2024).
pancreatic cancer (3 papers, 2020 to 2025). "The methylation status of GRAP2, ICAM3, A2ML1, MUC1, and MUC4 can influence the expression of these genes, which is associated with survival of pancreatic cancer." (PMID 33302876, 2020). "Among the upregulated proteins in the exosomes of patients with pancreatic cancer, exostosin-like glycosyltransferase 2 (EXTL2), α-2-macroglobulin like 1 (A2ML1), and Parkinson's disease protein 7 (PARK7) were the most significantly overexpressed." (PMID 40331617, 2025). "Previous studies based on the comprehensive analysis of genomics, epigenomics, transcriptomics, and clinical information of pancreatic cancer have demonstrated a significant negative correlation between A2ML1 gene expression level and methylation status." (PMID 37954860, 2023).
breast carcinoma (2 papers, 2020 to 2023). "Moreover, A2ML1 has been associated with the prognosis of lung, pancreatic, and breast cancer." (PMID 37954860, 2023). "Studies have established a correlation between α2-macroglobulin-like 1 (A2ML1) and the prognosis of lung, pancreatic, and breast cancers; however, research on its involvement in the pathogenesis of esophageal carcinoma remains limited." (PMID 37954860, 2023). "CCNE1, NPBWR1, A2ML1, EXO1 and TTK displayed good prognostic/diagnostic value for breast cancer and BRCA1/2-mutant breast cancer." (PMID 31998560, 2020). "Using the survival analysis, we found that CCNE1, NPBWR1, A2ML1 and TTK might act critical functions in the oncogenesis and progression of BRCA1/2-mutant breast cancer, reflected by their diagnostic efficacy for BRCA1/2 mutations and prognostic value as well." (PMID 31998560, 2020). "In our study, we found that NPBWR1 and A2ML1 have certain prognostic or diagnostic significance for breast cancer, and we thought that the two molecules also deserve further investigated, though their expression level in breast cancer tissues is not high enough overall." (PMID 31998560, 2020). "Although the NPBWR1, A2ML1 and C4orf51 displayed differential expression, their expression level in breast cancer tissues is still not high, which may be due to their own expression abundance or sensitivity of the detection probe." (PMID 31998560, 2020).
Hypertension (2 papers, 2021). The presence of chronic increased pressure in the systemic arterial system. "Of these genes, A2ML1, AGGF1, CBS, ECE1, GABRB3, GALNT2, MRPS6/SLC5A3, and SPG7 had documented associations with hypertension, ischemic stroke and methionine metabolism, atherosclerosis, and early-onset MI." (PMID 34252155, 2021). "Based on meta-analyses, A2ML1 was related to hypertension; ADRB2 and NOS3 jointly acted on sympathetic nervous system; while ADRB2 was related to hypertension in American Indians and involved in pathophysiology of hypertension in Yi population." (PMID 34297769, 2021).
lung squamous cell carcinoma (2 papers, 2019 to 2020). "In our study, we found that the expression of LINC00668 is associated with A2ML1 and DNAJC12; of which A2ML1 has been shown to be closely related to the treatment of lung squamous cell carcinoma and can be used as a potential prognostic biomarker." (PMID 31850229, 2019).
paraneoplastic pemphigus (2 papers, 2020 to 2023). Pemphigus is a group of chronic autoimmune skin diseases characterized by blisters formation on the outer layer of the skin and the mucous membranes. "A2ML1 has demonstrated clinical significance in paraneoplastic pemphigus (PNP), an autoimmune bullous disease characterized by pleomorphic mucosal skin lesions, mainly associated with lymphoproliferative tumors." (PMID 37954860, 2023). "The clinical significance of A2ML1 has been demonstrated in paraneoplastic pemphigus (PNP), an autoimmune bullous disease accompanied by a variety of benign or malignant tumors including non-Hodgkin lymphoma." (PMID 31998560, 2020).
RASopathies (2 papers, 2018 to 2021). "From the current understanding, the majority of reported pathogenic mutations in RASopathies are gain-of-function mutations, whereas one of the two A2ML1 variants in our study is a null mutation." (PMID 29402968, 2018). "A2ML1 was not excluded because according to our results A2ML1 interactome has a protein–protein association overlap with the rest of the RASopathy ́s interactomes above 25%, which is even higher than the one obtained for other RASopathy proteins." (PMID 34229750, 2021). "However, A2ML1 was not excluded because according to our results A2ML1 interactome has a protein–protein association overlap with the rest of the RASopathy interactomes above 25%, which is even higher than the one obtained for other RASopathy proteins." (PMID 34229750, 2021).
bronchiolitis obliterans (1 paper, 2010). "Nevertheless, based on the tissue distribution profile of A2ML1 and its lack of expression in pulmonary epithelium, it is unlikely that autoantibodies to A2ML1 contribute to bronchiolitis obliterans and respiratory failure, a frequent cause of death in PNP." (PMID 20805888, 2010).
bullous pemphigoid (1 paper, 2010). Bullous pemphigoid (BP) is the most common form of autoimmune bullous dermatosis. "We demonstrate that 10 PNP sera recognize alpha-2-macroglobuline-like-1 (A2ML1), while none of the control sera obtained from patients with bullous pemphigoid, pemphigus vulgaris, pemphigus foliaceus and normal subjects does." (PMID 20805888, 2010).
celiac disease (1 paper, 2024). An autoimmune genetic disorder with an unknown pattern of inheritance that primarily affects the digestive tract. "In addition, the promoter regions of Carboxylesterase 1 (CES1), alpha-2-macroglobulin like 1 (A2ML1) and Solute Carrier Family 39 Member 5 (SLC39A5) were significantly hypermethylated in celiac disease." (PMID 38780872, 2024).
esophageal squamous cell carcinoma (1 paper, 2023). Esophageal squamous cell carcinoma (ESCC) is a type of esophageal carcinoma (EC) that can affect any part of the esophagus, but is usually located in the upper or middle third. "Therefore, in this study, we aimed to investigate the role of A2ML1 in the progression of esophageal squamous cell carcinoma (ESCC)." (PMID 37954860, 2023).
lung carcinoma (1 paper, 2020). "Recently, a bioinformatics study pointed out the new use of A2ML1 as a diagnostic target for lung cancer." (PMID 31998560, 2020).
periodontitis (1 paper, 2022). An acute or chronic inflammatory process that affects the tissues that surround and support the teeth. "Previous research has shown that A2ML1 plays a beneficial role in the growth and the survival of syphilitic and periodontitis-associated treponemes." (PMID 35982087, 2022).
cancer (3 papers, 2020 to 2023). A tumor composed of atypical neoplastic, often pleomorphic cells that invade other tissues. "A bioinformatics study has reported the potential of A2ML1 in predicting cancer prognosis, with its expression linked to the tripartite motif containing 58/cg26157385 methylation." (PMID 37954860, 2023).
neoplasia (2 papers, 2010 to 2023). "The protein level of A2ML1 in ESCC tissues was significantly lower than that in normal esophageal tissues, and higher A2ML1 protein levels were associated with smaller ESCC tumor sizes and improved tumor-specific survival rates." (PMID 37954860, 2023). "Immunohistochemical staining was employed to assess the expression level of A2ML1 protein in both tumor and adjacent normal tissues of patients with ESCC." (PMID 37954860, 2023). "Similarly, A2ML1 played a role in tumor inhibition in mouse models." (PMID 37954860, 2023). "Moreover, high A2ML1 expression was correlated with tumor size (P < 0.01)." (PMID 37954860, 2023). "Future systematic studies with prospective cohorts of patients and detailed analysis of the immunological profile are needed to assess whether presence of anti-A2ML1 autoantibodies is associated with a particular PNP phenotype and organ involvement as well as a specific type of neoplasia." (PMID 20805888, 2010). "Higher levels of A2ML1 protein were correlated with smaller ESCC tumor size and improved tumor-specific survival rates." (PMID 37954860, 2023). "In view of the correlation between A2ML1 expression level and tumor size, as well as the experimental finding that A2ML1 overexpression inhibits ESCC cell proliferation and promotes apoptosis, we speculated that A2ML1 may participate in tumor cell growth regulation." (PMID 37954860, 2023).
bacterial infection (1 paper, 2020). "Therefore, it might be possible that PZP and A2ML1 play a different role in some regulatory mechanism for inflammation and bacterial infection between human and marmoset species." (PMID 32198464, 2020).
A2ML1 also shares sentences with these, for which no sentence is quoted: atherosclerosis (1 paper); bone marrow failure (1); cervical adenocarcinoma (1); cervical cancer (1); cervical squamous cell carcinoma (1); esophageal carcinoma (1); glioma (1); hematologic malignancies (1); infection (1); ischemic stroke (1); nicotine dependence (1); non-Hodgkin lymphoma (1); Noonan-related syndrome (1); otitis (1); pemphigus vulgaris (1); pregnancy disorder (1); respiratory failure (1).